ENTREP3 (endosomal transmembrane epsin interactor 3)
Synonyms: C1orf2; COTE1; FAM189B
Tractability: Antibody: UniProt predicts a signal peptide or a membrane-spanning region. PROTAC: ubiquitination databases record sites on it.
Gene: Protein-coding gene on chromosome 1 (155,247,205 to 155,255,795, reverse strand). Ensembl gene ENSG00000160767.
Subcellular location: Membrane
Subcellular location (Human Protein Atlas): Nucleoplasm
Gene Ontology:
Molecular function: protein binding; WW domain binding
Cellular component: nucleoplasm; membrane
Genetic constraint (gnomAD): Loss-of-function variants: 38 observed, 55.51 expected, observed/expected ratio (o/e) 0.68, 90% interval 0.53 to 0.9. The upper end of that interval is the gene's LOEUF score, 0.9, which puts it in group 3 of 6, group 1 being the genes least tolerant of losing a copy. Missense variants: 874 observed, 850.04 expected, observed/expected ratio (o/e) 1.03, 90% interval 0.97 to 1.09. Synonymous variants: 365 observed, 352.12 expected, observed/expected ratio (o/e) 1.04, 90% interval 0.95 to 1.13.
Homologues: Orthologues: chimpanzee ENTREP3 (99% identical), macaque ENTREP3 (99% identical), pig ENTREP3 (96% identical), dog ENTREP3 (95% identical), mouse Entrep3 (94% identical), rabbit ENTREP3 (94% identical), rat Entrep3 (94% identical), guinea pig ENTREP3 (93% identical), zebrafish fam189b (43% identical), tropical clawed frog ENTREP3 (32% identical). Paralogues in human: ENTREP2 (27% identical), ENTREP1 (24% identical).
Diseases named in the same sentence as ENTREP3 in open-access papers:
ENTREP3 is named in the same sentence as 14 diseases in open-access papers, as found by Europe PMC text mining. Sharing a sentence is not in itself a finding about the gene and the disease.
ENTREP3 shares sentences with these, for which no sentence is quoted: cancer (3 papers); gastric cancer (3); hepatocellular carcinoma (3); tumor (3); Gaucher disease (2); breast carcinoma (1); cholangiocarcinoma (1); gastric tumor (1); head and neck cancer (1); intrahepatic cholangiocarcinoma (1); liver cancer (1); lung carcinoma (1); Lymphatic Metastasis (1); small cell lung carcinoma (1).